ZNF236 (zinc finger protein 236)
Description:
May be involved in transcriptional regulation.
Synonyms: ZNF236A; ZNF236B
Tractability: PROTAC: ubiquitination databases record sites on it.
Gene: Protein-coding gene on chromosome 18 (76,822,557 to 76,972,901, forward strand). Ensembl gene ENSG00000130856.
Subcellular location: Nucleus
Subcellular location (Human Protein Atlas): Cell Junctions; Nucleoplasm; Cytosol
Gene Ontology:
Molecular function: protein binding; DNA-binding transcription factor activity, RNA polymerase II-specific; RNA polymerase II cis-regulatory region sequence-specific DNA binding
Biological process: cellular response to glucose stimulus; regulation of transcription by RNA polymerase II
Cellular component: nucleus
Genetic constraint (gnomAD): Loss-of-function variants: 46 observed, 180 expected, observed/expected ratio (o/e) 0.26, 90% interval 0.2 to 0.33. The upper end of that interval is the gene's LOEUF score, 0.33, which puts it in group 1 of 6, group 1 being the genes least tolerant of losing a copy. Missense variants: 1,703 observed, 2,360.6 expected, observed/expected ratio (o/e) 0.72, 90% interval 0.69 to 0.75. Synonymous variants: 886 observed, 934.79 expected, observed/expected ratio (o/e) 0.95, 90% interval 0.9 to 1.
Homologues: Orthologues: chimpanzee ZNF236 (99% identical), macaque ZNF236 (99% identical), guinea pig ZNF236 (90% identical), mouse Zfp236 (89% identical), pig ZNF236 (89% identical), rat Zfp236 (88% identical), rabbit ZNF236 (87% identical), dog ZNF236 (85% identical), tropical clawed frog znf236 (72% identical), zebrafish znf236 (55% identical), Drosophila melanogaster CG15073 (10% identical).
Diseases named in the same sentence as ZNF236 in open-access papers:
ZNF236 is named in the same sentence as 15 diseases in open-access papers, as found by Europe PMC text mining. Sharing a sentence is not in itself a finding about the gene and the disease. The quoted sentences say what the papers report.
cleft palate (1 paper, 2022). Cleft palate is a fissure type embryopathy that affects the soft and hard palate to varying degrees. "Recently, miRNA regulation for this gene was observed in a cleft palate-associated gene study, where ZNF236 overexpression was linked to cell proliferation." (PMID 36611892, 2022).
congenital aural atresia (1 paper, 2014). "However, deletion of a critical region on 18q23 that includes the ZNF407 gene and two other zinc finger genes (ZNF516 and ZNF236), among other genes, is correlated with congenital aural atresia (CAA), which manifests a subset of phenotypes recognized by the 18q deletion (18q-) syndrome." (PMID 24907849, 2014).
developmental delays (1 paper, 2022). "The region related to developmental delays and abnormal cerebral white matter development is 18q22.3q23, and the possible related pathogenic genes are ZNF236, ZNF516, MBP, GALR1 and lOC284276." (PMID 36123715, 2022).
diabetes (1 paper, 2020). "In Open Targets Genetics, genes near the ZBTB38, UBAP2 and ZNF236 loci show associations with various cancers, diabetes and obesity (no relevant mouse data available for these genes)." (PMID 33290408, 2020).
Intellectual disability (1 paper, 2022). "The deletion was the largest found in our dataset, spanning 13 Mb and two genes intolerant to truncating variants, ZNF236 and ZNF407 that were associated with chromosome 18q deletion syndrome (OMIM 601808), neurodevelopmental disorders, and intellectual disability, among others." (PMID 35678011, 2022).
cancer (4 papers, 2020 to 2023). A tumor composed of atypical neoplastic, often pleomorphic cells that invade other tissues. "The other 6 genes, GPR98, ZFYVE26, AHNAK2, APOB, ZNF236, and ODZ1, were all supported to be related to cancers by research." (PMID 33244318, 2020).
ZNF236 also shares sentences with these, for which no sentence is quoted: adenocarcinoma (1 paper); neurodegenerative disease (1); neurodevelopmental disorder (1); Obesity (1); ovarian serous cystadenocarcinoma (1); prostate carcinoma (1); schizophrenia (1); squamous cell carcinoma (1); Type 2 Diabetes (1).